CCDC184 (coiled-coil domain containing 184)
Synonyms: C12orf68; LOC387856
Tractability: PROTAC: its protein half-life has been measured.
Gene: Protein-coding gene on chromosome 12 (48,183,644 to 48,185,926, forward strand). Ensembl gene ENSG00000177875.
Subcellular location (Human Protein Atlas): Cytosol; Mitochondria
Gene Ontology:
Molecular function: protein binding
Cellular component: cytoplasm
Genetic constraint (gnomAD): Loss-of-function variants: 11 observed, 9.44 expected, observed/expected ratio (o/e) 1.16, 90% interval 0.73 to 1.8. That is too few expected variants to judge how well the gene tolerates losing a copy. Missense variants: 264 observed, 255.82 expected, observed/expected ratio (o/e) 1.03, 90% interval 0.93 to 1.14. Synonymous variants: 102 observed, 110.22 expected, observed/expected ratio (o/e) 0.93, 90% interval 0.79 to 1.09.
Homologues: Orthologues: chimpanzee CCDC184 (99% identical), macaque CCDC184 (96% identical), pig CCDC184 (93% identical), guinea pig CCDC184 (91% identical), rat Ccdc184 (91% identical), dog CCDC184 (91% identical), mouse Ccdc184 (89% identical).
Diseases named in the same sentence as CCDC184 in open-access papers:
CCDC184 is named in the same sentence as 2 diseases in open-access papers, as found by Europe PMC text mining. Sharing a sentence is not in itself a finding about the gene and the disease.
CCDC184 shares sentences with these, for which no sentence is quoted: Alzheimer disease (1 paper); dementia (1).